CD22 (CD22 molecule)
Diseases named in the same sentence as CD22 in open-access papers (continued):
Sharing a sentence is not in itself a finding about the gene and the disease.
Autoimmunity (18 papers, 2011 to 2025). The occurrence of an immune reaction against the organism's own cells or tissues. "Accordingly, natural genetic variants of CD22 in humans or CD22 deletion in mice predispose to autoimmunity." (PMID 39917832, 2025). "CD22 deficiency promotes the development of autoimmunity in autoimmune-susceptible mice and significantly increases autoantibody production, even in mice with partially downregulated CD22 expression (heterozygous CD22+/− mice)." (PMID 38711503, 2024). "Polymorphisms in the CD22 gene itself have also been linked to autoimmunity." (PMID 30323814, 2018). "The restricted expression of CD22 (Siglec‐2) on B cells has inspired researchers to target this receptor for instructing B‐cell tolerance or to dampen harmful B‐cell responses allergy or autoimmunity." (PMID 33752265, 2021). "The related Src kinase Lyn is responsible for phosphorylation of inhibitory receptors such as FcgRIIb and CD22 (Siglec-2) in lymphocytes and Lyn KO mice develop autoimmunity." (PMID 34497606, 2021). "Another new approach to induce antigen-specific suppression and to treat autoimmunity in the future is the usage of liposomal nanoparticles that display antigen and glycan ligands for the inhibitory receptor CD22." (PMID 30559744, 2018). "The role of CD22 in regulating MZ B cells and a possible link between MZ B cell decrease and increased autoimmunity needs further elucidation." (PMID 30323814, 2018). "A combination of predisposing factors such as TLR signals along with the unmasking of CD22 at the TR stage would favor the activation of poly/autoreactive TR B cells and thus contribute to the development of autoimmunity." (PMID 30323814, 2018). "This review summarizes the role of CD22 and Siglec-G in regulating B-cell receptor signaling, membrane distribution with the importance of ligand binding, preventing autoimmunity and the role of CD22 beyond the naïve B-cell stage." (PMID 30559744, 2018). "The CD22 ectodomain adopts an extended conformation that facilitates concomitant CD22 nanocluster formation on B cells and binding to trans ligands to avert autoimmunity in mammals." (PMID 28970495, 2017). "CD22 inhibits B-cell receptor induced signaling and has a role in preventing autoimmunity." (PMID 33353204, 2020). "Modeling suggests that CD22 binding to 9-O-acetylated Sia is sterically impeded by W128 located in strand G of the binding pocket, providing structural insights into why acetylation of Sia on self-antigens prevents CD22 recognition and increases B-cell-mediated autoimmunity." (PMID 28970495, 2017). "Another important B cell molecule which has an effect on autoimmunity development is the CD22." (PMID 24187614, 2013). "Understanding the function of CD22 may, therefore, suggest methods for modulating humoral immunity and aid in discovering treatments for autoimmunity." (PMID 24187614, 2013). "The role of CD22 in infections has not been widely studied but to be in line with the observations on autoimmunity, it might be predicted that loss of CD22 would not have a negative impact on the outcome of acute infection." (PMID 32324805, 2020). "Interestingly the lack of CD22 leads to a pre-activated B cell phenotype with a higher calcium mobilization, but this does not cause autoimmunity on a pure C57BL/6 background, while autoimmunity has been observed on a mixed 129 x C57BL/6 background." (PMID 30559744, 2018). "These animals can now be used to investigate the mode of action and side effects of anti-human CD22 therapeutic antibodies, immunotoxins or CAR T cells and to further optimize therapies of B-cell malignancies and autoimmunity." (PMID 30559744, 2018). "The ability of CD22 to regulate both BCR and TLRs represents an attractive therapeutic strategy for manipulating B cell responses in autoimmunity." (PMID 30323814, 2018).
Autoimmunity (continued). "This toleragenic regulation by CD22 and Siglec-G/10 has been proposed as a mechanism for host discrimination between self and non-self, safeguarding against the development of autoimmunity." (PMID 30294329, 2018). "Genetic factors affecting CD22 or TLR7 expression may affect the ability of CD22 to regulate TLR7-mediated B cell activation and contribute to autoimmunity." (PMID 30323814, 2018). "More specifically, whereas nether CD22-deficient nor Siglec-G-deficient mice on a pure C57BL/6 or BALB/c background, respectively, presented autoimmunity, CD22 x Siglec-G double-deficient mice presented increased B1 cell numbers and developed systemic autoimmunity." (PMID 34071314, 2021). "We currently do not know how the degree of CD22 glycosylation and terminal sialylation creating CD22 homotypic cis ligands varies in different B cell subsets and how it may be altered in B cell diseases such as cancer and autoimmunity." (PMID 31019513, 2019).
chronic lymphocytic leukemia (18 papers, 2011 to 2025). "Chronic lymphocytic leukaemia B cells express low levels of CD22 and were less susceptible to inhibition by RBC, which may contribute to their activated phenotype." (PMID 33728669, 2021). "Although the low level of CD22 expression on the B cells in patients with chronic lymphocytic leukemia (CLL) has been documented, CD22’s role and its downregulation mechanism in CLL are yet to be fully studied." (PMID 40054694, 2025). "Immunophenotype of MCL cells is also characterized by the co-expression of CD5 and pan B-cell antigens (CD19, CD20, CD22, and CD24), which are also detectable in CLL/small lymphocytic lymphoma." (PMID 36624655, 2023). "CD19 is not only expressed in NHL and in B cell chronic lymphocytic leukemia (B-CLL) like CD20 and CD22, but also in B-ALL." (PMID 37501154, 2023). "Immunohistochemically, small lymphocytic lymphoma expresses IgM/IgD, CD20, CD22, CD5, CD19, CD79a, CD23, CD43 and CD11c." (PMID 22333190, 2012). "Bryostatin 1 was administrated (by 72 h continuous infusion every 2 weeks at a dose of 120 μg/m2 per course) to 25 patients with relapsed, low-grade non-Hodgkin’s lymphoma or chronic lymphocytic leukemia (CLL) and induced the upregulation of the co-expression of CD11c/CD22 on CD20+ cells." (PMID 34198841, 2021). "In B-cell chronic lymphocytic leukemia (B-CLL), bryostatin has been shown in vitro to promote differentiation toward a hairy cell leukemia (HCL)-like phenotype, marked by increased expression of CD11c, CD22, and tartrate-resistant acid phosphatase activity." (PMID 40869085, 2025). "The IC50 values on primary chronic lymphocytic leukaemia (CLL) samples varied from 275–875 nM, without any effect on CD22-negative cells from healthy donors or CLL-patients." (PMID 30783518, 2019). "Chronic lymphocytic leukemia (CLL) is a common disorder characterized by the monoclonal accumulation of B lymphocytes with a distinct phenotype (CD5-positive, CD23-positive, CD22-negative and low level of surface Ig) and a highly variable clinical course." (PMID 21897877, 2011).
acute myeloid leukemia (17 papers, 2017 to 2025). Acute myeloid leukemia (AML) is a group of neoplasms arising from precursor cells committed to the myeloid cell-line differentiation. "A similar product is being evaluated in B-ALL and acute myeloid leukemia (AML) patients targeting CD22 and CD123, respectively." (PMID 40981226, 2025). "Siglec-2 (CD22) is upregulated in approximately 90% of acute myeloid leukemia (AML) cases." (PMID 38254780, 2024). "For instance, dual-targeting CD19/CD22 CAR T-cell therapy has shown enhanced OS and progression-free survival (PFS) in Acute Myeloid Leukemia (AML) patients compared to single-antigen CAR T-cell therapy." (PMID 38612592, 2024). "Initial Pre-clinical studies focusing on hematological cancers, targeting CD22 or CD33 in lymphoma and acute myeloid leukemia (AML), respectively, demonstrated promising anti-tumor activity." (PMID 36726355, 2022). "Among the currently FDA-approved antibody drug conjugates (ADCs), Mylotarg and Besponsa, which comprise the pH-sensitive hydrazone linkers derived from amino groups in drugs, target relapsed CD33 + acute myeloid leukemia (AML) and CD22 + B-cell acute lymphoblastic leukemia (B-ALL), respectively." (PMID 39054545, 2024). "As a control, the acute myeloid leukemia cell line MOLM13 cells did not express CD22 on the surface." (PMID 34667217, 2021). "In the preclinical studies, BiKE has been effectively used to target CD19/CD22 on B cell non-Hodgkin's lymphoma, CD33 on acute myeloid leukemia (AML) and myelodysplastic syndromes (MDS), EpCAM on various carcinomas, and CD133 on cancer stem cells." (PMID 39415291, 2024). "Notably, SOS is also an important side effect of gemtuzumab ozogamicin (GO), a CD33-calicheamicin ADC approved for the treatment of acute myeloid leukemia (AML), suggesting that this toxicity is related to the common cytotoxic payload calicheamicin and not specific to either CD22 or CD33 targeting." (PMID 37600823, 2023).
breast carcinoma (10 papers, 2015 to 2025). "High levels of Klhl24, Hbp1, Crebrf, Ypel2, CD22 and Ypel3 were correlated with better outcomes, whereas lower levels of Gdf15, Cdc25a, Ddit4 and Psat1 were associated with better prognosis in breast cancer patients." (PMID 34990474, 2022). "Bioinformatic analysis was performed to evaluate the expression of CD22 in breast carcinoma and normal tissues." (PMID 36768478, 2023). "When CD22 expression was investigated in breast cancer by Gene Expression Profiling Interactive Analysis (GEPIA) online database, the level of CD22 expression was slightly higher in breast cancer tissues than that in normal tissues." (PMID 36768478, 2023). "Differential gene expression analysis of TCGA data revealed that CD22 is among the upregulated differentially expressed genes (DEGs) with high expression in breast cancer, as compared to normal breast tissues." (PMID 36768478, 2023). "More testing experiments, such as fluorescence-activated cell sorting, should be carried out in the future to identify the surface expression model of CD22 in breast cancer." (PMID 36768478, 2023). "What’s more, our group has published another paper to indicate CD22 expression in breast cancer." (PMID 37817249, 2023). "Additionally, online bioinformatics web tools (GEPIA and TNM plot) were used to evaluate the expression of CD22 in breast carcinoma and normal tissues." (PMID 36768478, 2023). "CD22-mediated B-cell receptor (BCR) regulation, initial triggering of complement, scavenging of heme from plasma, and immunoregulatory interactions between lymphoid–nonlymphoid cell pathways were significantly enriched in low-risk breast cancer." (PMID 36936412, 2023). "However, as a protein ectopic expressed glycoprotein, the glycosylation of CD22 in breast cancer cells may be different from B cells." (PMID 36768478, 2023). "Conversely, in both breast cancer cell lines, O-desmethyltramadol consistently downregulated the expression of SLC16A1, CD22, NUPR1, ASNS, and DDIT3." (PMID 40362379, 2025). "The presence of CD20+CD22+ADAM28+ B cells in the TLSs was verified in multiple types of cancers, including colorectal cancer (CRC), breast cancer, skin squamous cell cancer (SCC), and renal clear cell cancer (RCC)." (PMID 35634306, 2022). "Our laboratory has also recently developed nanoparticles for selective uptake of CD22 overexpressing B-cell malignancies and HER2 overexpressing breast cancer, proving both to be other possible targets for liposomes designed through the same platform." (PMID 33138841, 2020). "A comprehensive examination of breast cancer cell lines (BT549, MDA-MB-231, MCF7) for expression of CD22 by WB and IF staining, followed by IHC staining of 97 TNBC specimens, showed that CD22 is widely expressed in the cytoplasm and cell membrane of TNBC cells." (PMID 36768478, 2023). "Heatmaps of CD22 gene expression clearly showed high expression of CD22 in most breast cancer tissue samples and that it reduced or had no expression in normal tissues." (PMID 36768478, 2023). "Additionally, the survival plot for CD22 expression and overall survival of breast cancer patients from GEPIA was also not significant (p = 0.09)." (PMID 36768478, 2023).
lung carcinoma (9 papers, 2015 to 2023). "Tuscano previously characterized the expression of CD22 in lung cancer cells and patient samples, identifying CD22 as a target for therapeutic intervention in lung cancer." (PMID 33796453, 2021). "CD22 expression has been exclusively described in B cells until recently when ectopic expression of CD22 was demonstrated in lung cancer cells." (PMID 25957418, 2015). "Besides, it is reported in some studies that CD22 exerts an important part in lung cancer." (PMID 34026619, 2021). "Finally, VEGFR2, MAGE-A1, MAGE-A4, PSCA, AXL, Claudin 18.2, TGFB, CD22, ROR1, OX40, DLL3, MSLN, and EpCAM are being targeted in CAR-T cell clinical trials for lung cancer." (PMID 35455052, 2022). "However, recent studies repeating this experiment found that CD22 was not expressed at measurable levels on the surface of lung cancer cells, and that tumor cells could not be killed by anti-CD22 immunotoxins." (PMID 33796453, 2021).
melanoma (9 papers, 2014 to 2025). A malignant, usually aggressive tumor composed of atypical, neoplastic melanocytes. "CD20+ and CD22+ B cell levels are significantly higher in melanoma patients than in healthy individuals, with their primary role being antibody production against melanoma-associated antigens." (PMID 40136652, 2025). "The mutation frequency of SIGLEC7 is up to 8% in melanoma, whereas those of SIGLEC1 and CD22 are up to 7%." (PMID 37207210, 2023). "PBMCs from patients with melanoma incubated with melanoma antigen-coated beads were screened to identify mature CD19/CD22+ B cells recognizing antigen-coated beads." (PMID 29628923, 2018). "Subsets of circulating (CD22+) B cells in patients with melanoma and healthy volunteers harbor skin homing potential, based on expression of CLA28." (PMID 27411958, 2016). "We found that a small proportion of circulating CD45+CD3-CD14-CD19+CD22+B cells in healthy volunteers (n = 24) and patients with melanoma (n = 49) express the skin-homing Cutaneous Leucocyte-associated Antigen (CLA)." (PMID 27411958, 2016). "We report circulating skin-homing CD22+CLA+B cells in healthy volunteers and melanoma patients (n = 73) and CD22+ cells in melanoma and normal skin samples (n = 189)." (PMID 27411958, 2016). "CD22+ infiltrates were found in 37.6% of melanomas (27% cutaneous lesions, 49.1% lymph node metastases, 38% distant metastases), with ~10% of melanomas featuring denser B cell infiltrating populations (>10 cells per high powered field)." (PMID 27411958, 2016). "The frequencies of circulating IgG4+ peripheral blood B cells (IgG4+CD45+CD22+CD19+CD3−CD14−) in melanoma patients with melanoma compared to those from healthy volunteers were determined by flow cytometric analyses." (PMID 26451312, 2015). "Immunohistochemical evaluations revealed CD22+ cells in normal skins and melanomas (n = 189)." (PMID 27411958, 2016). "CD22+ B cells are enriched in melanoma lesions compared to healthy skin, and CD20 and CD22 mRNA expression is further enhanced with metastasis, indicating the presence of a pronounced humoral immune response in melanoma." (PMID 33569063, 2020). "Increased relative expression of CD20, CD22 and AID in metastatic compared with primary melanoma were also found by analyses of the Cancer Genome Atlas (TCGA) database." (PMID 27411958, 2016). "Gene expression analyses of publically-available data (n = 234 GEO, n = 384 TCGA) confirmed heightened humoral responses (CD20, CD22, AID) in melanoma." (PMID 27411958, 2016).
acute leukemia (7 papers, 2020 to 2025). A clonal (malignant) hematopoietic disorder with an acute onset, affecting the bone marrow and the peripheral blood. "These associations between CD22 positivity and HLA alleles indirectly suggest a higher specificity for acute leukemias, despite their potential identification in other pathological conditions." (PMID 39329950, 2024). "The more robust homogeneous expression of CD19 compared to CD22 in pediatric acute leukemias may be a cause of these differences in resistance mechanisms." (PMID 34113750, 2020). "CD22 is generally regarded as a poor prognostic marker in acute leukemia." (PMID 40382561, 2025). "Our results show the efficacy of CD19/CD22 CAR T cells in adults with acute leukemia." (PMID 32245502, 2020). "We previously reported that cancer cells from the most common type of childhood cancer, namely, a form of acute leukemia known as B-ALL, are characterized by an abnormality known as CD22 exon 12 deletion." (PMID 36900389, 2023). "The WHO 2016 updated classification of hematological malignancies of myeloid neoplasms and acute leukemia has defined the criteria for assignment of the B-ALL lineage by FC on the basis of the intensity of expression of four key markers: CD19, CD79a, cytoplasmic CD22, and CD10." (PMID 34706776, 2021).
mantle cell lymphoma (7 papers, 2010 to 2025). Mantle cell lymphoma is a rare form of malignant non-Hodgkin lymphoma affecting B lymphocytes in the lymph nodes in a region called the ``mantle zone''. "Discriminating WM from chronic lymphocytic leukemia (CLL), mantle cell lymphoma (MCL), and follicular lymphoma involves noting the presence of CD19, CD20, CD22, CD79α, and CD138 cell expression and lack of CD5, CD10, and CD23." (PMID 36232447, 2022). "Mantle cell lymphoma (MCL), an aggressive B cell malignancy, is characterized by the abnormal proliferation and accumulation of CD5/CD20/CD22 positive, CD23 negative B cells in various hematopoietic tissues, with or without peripheral blood involvement." (PMID 20532179, 2010).
Alzheimer disease (5 papers, 2019 to 2024). A progressive, neurodegenerative disease characterized by loss of function and death of nerve cells in several areas of the brain leading to loss of cognitive function such as memory and language. "The plasma levels of soluble CD22 are elevated in patients with Alzheimer’s disease, and its level was correlated with brain Ab burden, cerebrospinal fluid (CSF) p-tau levels, and baseline cognitive impairment." (PMID 38711503, 2024). "CD22 has been suggested to contribute to Alzheimer's disease (AD) pathogenesis by inhibiting microglial amyloid β (Aβ) phagocytosis." (PMID 35363517, 2022). "However, recent studies have shown elevated expression of CD22 in the CNS of Alzheimer's disease (AD) and Niemann–Pick disease patients." (PMID 38739106, 2024). "Moreover, a SNP in INPP5D, the gene coding for the CD22 downstream signaling partner SHIP-1, was associated with late-onset Alzheimer’s disease (LOAD)." (PMID 34140954, 2021).